NRG4 (neuregulin 4)
Diseases named in the same sentence as NRG4 in open-access papers (continued):
Sharing a sentence is not in itself a finding about the gene and the disease.
morbid obesity (1 paper, 2024). An excess of body weight, normally defined as an individual with a body mass index greater than 35 or a body weight greater than one hundred percent of ideal body weight. "Low circulating Nrg4 levels may aid in the prediction of morbid obesity, and subsequent GDM, T2DM, NAFLD, and CVD." (PMID 39162358, 2024).
Myocardial fibrosis (1 paper, 2022). "A recent study has shown that upregulation of Nrg4 gene expression can inhibit cardiomyocyte apoptosis, reverse myocardial fibrosis and play a cardioprotective role in spontaneously hypertensive rats." (PMID 36221104, 2022).
Sepsis (1 paper, 2025). Sepsis is defined as life-threatening organ dysfunction caused by a dysregulated host response to infection. "Recent evidence highlights ferroptosis as a key factor in the progression of sepsis-induced liver injury, implying a potential regulatory function for Nrg4 in modulating ferroptosis in this context." (PMID 39956880, 2025). "After sepsis, Nrg4 expression in mouse BAT increased, and plasma levels of Nrg4 rose, consistent with findings from drug-activated BAT." (PMID 39956880, 2025). "Our study is the first to show that BAT can reduce liver ferroptosis by secreting Nrg4, thereby protecting against sepsis-induced liver injury." (PMID 39956880, 2025). "Our research has pinpointed Nrg4 as a crucial liver-protective protein that is secreted by BAT subsequent to sepsis-induced liver damage." (PMID 39956880, 2025). "This study demonstrates that sepsis induces Nrg4 secretion from mouse BAT, which enters the circulation and offers protection to the liver." (PMID 39956880, 2025). "Based on this, we propose that Nrg4 may be a key factor through which BAT exerts its protective effects on the liver during sepsis." (PMID 39956880, 2025). "Future therapies targeting BAT activation and Nrg4 could potentially mitigate sepsis-induced liver damage, offering new insights into treatment strategies." (PMID 39956880, 2025). "The findings indicate that BAT-derived Nrg4 suppresses ferroptosis and attenuates sepsis-induced liver injury by promoting the expression of SLC7A11, GSH, and GPX4, suggesting potential therapeutic application of BAT activation and its secreted Nrg4 in treating septic liver injury." (PMID 39956880, 2025). "To investigate whether Nrg4 mitigates sepsis-induced liver injury, we administered Nrg4 protein to CLP mice." (PMID 39956880, 2025). "This study highlights the crosstalk between BAT and septic liver injury, and future research could focus on using BAT activation or Nrg4 as a therapeutic approach to mitigate liver injury in sepsis, providing valuable guidance for treating sepsis-related liver damage." (PMID 39956880, 2025). "Additionally, Nrg4 role in damage to other organs during sepsis remains understudied." (PMID 39956880, 2025). "In summary, sepsis induces both BAT thermogenesis and Nrg4 secretion; however, CL316243 further enhances Nrg4 release from BAT." (PMID 39956880, 2025). "Previous experiments have demonstrated that both sepsis and CL316243 can stimulate BAT to secrete Nrg4." (PMID 39956880, 2025). "Compared with vehicle-treated CLP mice, recombinant Nrg4 (rNrg4) administration markedly improved survival rates and reduced MSS, indicating alleviation of sepsis symptoms." (PMID 39956880, 2025). "Building on previous results, we confirmed that sepsis triggers BAT activation, leading to the secretion of Nrg4, which mitigates liver ferroptosis and provides protection against liver injury." (PMID 39956880, 2025). "The precise relationship between Nrg4 secretion and BAT thermogenic activation has not been fully explored, nor is it clear whether Nrg4 is a critical mediator of protection against sepsis-induced liver damage." (PMID 39956880, 2025).
type 1 diabetes (1 paper, 2022). "Our previous studies have shown that Nrg4 activated autophagy in type 1 diabetes." (PMID 36221104, 2022). "Four weeks after the establishment of a model of type 1 diabetes in mice, the mice received Nrg4 treatment (with or without an autophagy inhibitor) for another 4 weeks." (PMID 36221104, 2022).
type 2 diabetic nephropathy (1 paper, 2023). "Therefore, the purpose of this study was to evaluate serum HCY and NRG4 levels in T2DM patients with DN and to explore the predictive value of serum HCY combined with NRG4 levels in the early detection of type 2 diabetic nephropathy." (PMID 36983737, 2023).
metabolic disorders (26 papers, 2016 to 2024). "Secondly, there is limited evidence on the causal relationship between circulating Nrg4 levels and the development of metabolic diseases." (PMID 39162358, 2024). "Although there is a growing large body of clinical evidence demonstrating the association between circulating Nrg4 levels and various metabolic diseases, there are several limitations to be acknowledged." (PMID 39162358, 2024). "Nrg4 deficiency impairs beige fat induction and renders mice more susceptible to diet-induced metabolic disorders under mild cold conditions." (PMID 38015639, 2024). "Therefore, we summarize here the mechanisms underlying the actions of Nrg4 in metabolism and their effects on diverse metabolic diseases in preclinical and clinical settings and suggest possible directions for future investigations." (PMID 36703934, 2022). "Moreover, clinical studies have also found that Nrg4 is associated with metabolic disorders." (PMID 36221104, 2022). "In previous studies, we identified NRG4 as a brown fat–enriched secreted factor that protects mice from diet-induced metabolic disorders." (PMID 38015639, 2024). "For instance, it has been documented that Neuregulin 4 (Nrg4) primarily secreted from brown adipose tissue (BAT) and adipsin mainly synthesized in the white adipose tissue (WAT) are associated with metabolic diseases." (PMID 34017266, 2021). "However, the predictive role of Nrg4 on metabolic disease, particularly CVD should be compared with other conventional biomarkers such as C-reactive protein (CRP) for further investigations." (PMID 39162358, 2024). "This indicates that genetic variation in the population generates an aberrant function of NRG4, which could serve as either a risk factor or a protective factor for NAFLD and associated metabolic disorders." (PMID 39872218, 2024). "Moreover, our work revealed that the administration of recombinant NRG4-Fc fusion protein promotes beige fat induction and alleviates diet-induced metabolic disorders." (PMID 38015639, 2024). "This might explain the findings from most studies showing that circulating levels of Nrg4 were low or reduced in patients with diverse metabolic disorders." (PMID 39162358, 2024). "Taken together, these findings suggest that Nrg4 levels might depend on the evolution and developmental stage of metabolic disorders." (PMID 39162358, 2024). "In terms of metabolic disorders, in addition to the body surface features of overweight and increased body fat, hematological indicators showed that serum insulin, serum NRG4, and serum C-peptide were significantly increased, and serum irisin was significantly decreased." (PMID 34427289, 2021). "Nrg4 mutant mice are viable, but display metabolic disorders." (PMID 34350179, 2021). "They showed that transgenic expression of Nrg4 recovers diet-induced metabolic disorders." (PMID 32242042, 2020). "Because the Nrg4 expression patterns might be evidently different among those tissues, the expression of Nrg4 in circulation under the condition of metabolic disorders could be distinct from that in adipose tissues." (PMID 31815951, 2019). "However, the relationship between circulating Nrg4 and metabolic disorder in human subjects remains largely unclear." (PMID 27772531, 2016). "Therefore, Nrg4 may represent a future endocrine target for the treatment of metabolic disorders." (PMID 36703934, 2022). "Finally, a recent study suggested that genetic variations in neuregulin (NRG4) may give rise to mutant proteins with altered functions and that impaired or enhanced Nrg4 function could be either a risk factor or a protective factor for NAFLD and associated metabolic disorders." (PMID 38331795, 2024). "Nrg4 as an adipokine enriched in BAT has been revealed to potentiate BAT-related thermogenesis by modulating sympathetic innervation of adipose tissue and has demonstrated potential as a therapeutic target in multiple metabolic disorders." (PMID 36703934, 2022).
cardiovascular disease (10 papers, 2016 to 2025). "Recently, several novel proteins secreted from adipocytes, such as Nrg4 and adipsin have been identified to play a role in modulate systemic metabolic homeostasis and are associated with MetS and cardiovascular disease." (PMID 34017266, 2021). "Lower serum NRG4 has been associated with early detection of vascular abnormalities, such as increased carotid intima media thickness and atherosclerotic plaque, particularly in individuals at high risk of subclinical cardiovascular disease." (PMID 40149686, 2025).
tumor (10 papers, 2014 to 2026). "NRG4, as an adipose endocrine factor, could inhibit the expansion of macrophages with tumor-associated macrophage molecular characteristics and inhibit the depletion of CD8+ T cells caused by tumor-associated macrophages, thereby exerting anti-hepatocellular carcinoma effects." (PMID 41200178, 2025). "ERBB2 demonstrated a moderate linear correlation with the maximal tumor diameter (Spearman’s ρ = 0.432, p = 0.001), and NRG4 demonstrated a moderate linear correlation with the number of tumors (Spearman’s ρ = 0.558, p < 0.001)." (PMID 37174100, 2023). "The univariate analysis of survival demonstrated that HBV infection, Child–Pugh class, maximal tumor diameter, AFP, BCLC stage, treatment modality, ERBB2, and NRG4 were significant risk factors." (PMID 37174100, 2023). "To better illustrate the magnitude of NRG4 downregulation in the tumor tissue, we plotted the NRG4 down- or upregulation for each individual patient." (PMID 24728052, 2014). "Considering all the patients showing downregulation of total HER4 in their tumor tissue, in 82% of these NRG4 was also downregulation and in 86% one or more of the EGFR-shared ligands (HB-EGF, epiregulin, betacellulin) was upregulated." (PMID 24728052, 2014). "Furthermore, ERBB2 (HR, 2.338; p = 0.002) and NRG4 (HR, 431.763; p = 0.001) were independent prognostic factors for tumor recurrence." (PMID 37174100, 2023). "Interestingly, we found the mRNA expression of HER4 (p = 0.0002) and its ligand NRG4 (p = 0.0009) to be downregulated in the tumor tissue compared to the matched normal tissue." (PMID 24728052, 2014). "We found a marked downregulation of both HER4 and its activating ligand NRG4 in tumor tissue." (PMID 24728052, 2014). "Further construction of human Nrg4-Fc fusion protein revealed remarkably reduced induction of NASH-associated macrophages and T-cell depletion-related gene expression in the liver, demonstrating its potent inhibitory effect on the tumor-prone microenvironment in mice." (PMID 36703934, 2022). "This study aimed to evaluate the relationship between serum ERBB2, NRG4, and MIG6 levels and tumor characteristics, overall survival, and tumor recurrence to determine the potential prognostic value of these signaling molecules for HCC." (PMID 37174100, 2023). "In this study, the serum levels of ERBB2 and NRG4, which are involved in the EGFR signaling pathway, correlated with tumor characteristics." (PMID 37174100, 2023). "Based on the results of this study, which showed a significant relationship between ERBB2, NRG4, and MIG6 and tumor characteristics, we further evaluated the predictive performance of these potential biomarkers." (PMID 37174100, 2023). "ERBB2, NRG4, and MIG6 serum levels were compared based on tumor characteristics, including BCLC stage, tumor-maximal diameter, and the number of tumors, using the Kruskal–Wallis test and bivariate (Spearman) correlation." (PMID 37174100, 2023). "In the present study, we revealed that serum ERBB2 and neuregulin 4 (NGR4) are independent prognostic factors for survival and tumor recurrence and suggested a possible synergistic effect between these two prognostic factors." (PMID 37174100, 2023). "It was demonstrated that there was a strong induction of tumor-like macrophages and exhaustion of CD8+ T cells (cytotoxic T lymphocytes) in NASH, and Nrg4 knockout mice were shown to exacerbate the deregulation of the hepatic immune microenvironment." (PMID 36703934, 2022). "Amongst these are notable tumor related genes AKT3, CDKN1A, ESR1, FOXO1, TSC2, ERBB3, and NRG4." (PMID 40522948, 2025). "The combined differential tumor versus normal tissue expression of two genes and their vectorial summation correlated with the PFS of three patients treated with afatinib as monotherapy: NRG4 and NRG2 (r = −1 p = 8.4E−04)." (PMID 33911192, 2021).
tumor (continued). "One possible mechanism is that in the presence of high ERBB2 levels, ERBB4 with bound NRG4 may form ERBB2:ERBB4 heterodimers, which possess oncogenic activity, rather than ERBB4:ERBB4 homodimers, which function as tumor suppressors." (PMID 37174100, 2023).
cancer (5 papers, 2017 to 2025). A tumor composed of atypical neoplastic, often pleomorphic cells that invade other tissues. "In addition, TPAC cancer cells overexpressed Fgf9, which promotes proliferation of neuronal precursors, Nrg1, which has been shown to drive proliferation and/or induce myelin differentiation, and Nrg4, which is involved in the establishment of early sensory innervation in the skin." (PMID 37607005, 2023). "In conclusion, here we propose a provocative therapy based on the combinatorial administration of a growth factor, namely NRG4, in combination with anti-ERBB2 antibodies as a novel anti-cancer strategy based on specific activation of ERBB4-ERBB4 homodimers." (PMID 35664762, 2022). "We propose a provocative paradigm shift in the field of growth factors in cancer progression, suggesting the administration of ERBB4 ligands, such as Neuregulin 4, as a strategy to improve the efficacy of anti-ERBB2 agents." (PMID 35664762, 2022).
infection (1 paper, 2024). The state of being infected such as from the introduction of a foreign agent such as serum, vaccine, antigenic substance or organism. "Collectively, these data indicated that Sult1e1 and Nrg4 are potential host response factors for DENV N10 strain infection." (PMID 39599894, 2024). "More importantly, during N10 infection, MoMFs as senders transmitted signals via Nrg2, which in turn triggered Nrg4 signaling in hepatocytes." (PMID 39599894, 2024).
neurodegenerative disease (1 paper, 2021). A disorder of the central nervous system characterized by gradual and progressive loss of neural tissue and neurologic function. "Thus, it will be interesting to ascertain how the putative NRG4/ErbB4 autocrine loop is regulated in pyramidal neurons and investigate how NRG4 contributes to the pathogenesis of particular neurodegenerative diseases such as AD." (PMID 33897409, 2021).
NRG4 also shares sentences with these, for which no sentence is quoted: gestational diabetes mellitus (7 papers); Hypertension (5); Hyperinsulinemia (3); ulcerative colitis (3); diabetic retinopathy (2); Glucose intolerance (2); Nephropathy (2); Acute hepatitis (1); autonomic neuropathy (1); bipolar disorder (1); chronic kidney disease (1); dengue disease (1); depression (1); endothelial dysfunction (1); Erythroblastic Leukemia (1); germ cell tumor (1); inflammation (1); myocardial ischemia (1); necrotizing enterocolitis (1); neurodevelopmental disorder (1); neurological disorders (1); non-alcoholic fatty liver (1); peripheral arterial disease (1); peripheral neuropathy (1); prediabetes (1); psychiatric disorder (1); retinopathy (1); unstable angina pectoris (1).